HIF1A (hypoxia inducible factor 1 subunit alpha)
Diseases named in the same sentence as HIF1A in open-access papers (continued):
Sharing a sentence is not in itself a finding about the gene and the disease.
glioma (continued). "With respect to neurooncology, Tateishi and colleagues examined the interest of using [62Cu]-ATSM for glioma grading and correlated [62Cu]-ATSM uptake with HIF-1α expression in glioma patients." (PMID 26347870, 2015). "Here we report for the first time that sphingomab inhibits HIF-1α accumulation and activity under hypoxia in various cell models (prostate, lung, glioma)." (PMID 25915662, 2015). "Ectopic expression of CIDEA triggered apoptosis, activated JNK, decreased HIF-1α activation and increased PPARγ levels in glioma cells." (PMID 27551468, 2015). "In a glioma cell line, gene silencing of HIF-1α can downregulate MMP-2/MMP-9 to suppress cell migration and invasion into adjacent normal tissue." (PMID 25816356, 2015). "The decrease of HIF-1α expression in GBM cells is also another potential mechanism to explain diminished proliferation as it is now clearly established in glioma that HIF-1α inhibition induces a decreased proliferation and survival." (PMID 25867026, 2015). "In glioma patients, [18F]-RP-170 was compared to ptO2 and HIF-1α immunostaining and a selectivity of this tracer for hypoxia was observed." (PMID 26347870, 2015). "Supporting these studies, the inhibition of HIF1α through RNA interference results in a reduction of glioma growth." (PMID 25884993, 2015). "mIDH1-GL261 gliomas appeared macroscopically more hemorrhagic than pGL261-gliomas and showed increased levels of HIF-1α and VEGF." (PMID 25849072, 2015). "In recent studies, hypoxia was confirmed to promote the VM formation of glioma cells, and the induced HIF-1α and VEGF-A expression was suggested a mechanism involved in this process." (PMID 25667663, 2015). "We explore for the first time here the multiple roles of IGFBP2 and IGFI, their complex interactions with HIF1α, and their importance in glioma progression." (PMID 25884993, 2015). "OKN-007-induced decreases in Glut-1 and HIF-1α levels seemed to be similar in both F98 and U87 glioma models, whereas increased apoptosis seemed to be more elevated in the F98 gliomas compared to the U87 tumors." (PMID 26248280, 2015). "Some roles for HIF1α in glioma progression and in the insulin signaling pathway specifically have been identified: HIF1α promotes malignant cell growth, and elevated expression of HIF1α has been strongly correlated to tumor malignancy." (PMID 25884993, 2015). "We found that glioma tissues exhibited stronger immunohistochemical signals for both HIF1a and LC3B compared with normal tissues." (PMID 26536662, 2015). "Western blot analysis was used to determine the endogenous expression levels of HIF-1α or β-catenin in the glioma cell lysates used in these experiments." (PMID 24650032, 2014). "To further elucidate the underlying mechanism of C6 glioma cells transdifferentiating into ECs, we evaluated the protein expression of HIF-1α, Notch1, Flk1, and p-Flk1 in glioma tissue and C6 glioma cells by Western blot." (PMID 24722469, 2014). "Further, the maintenance of glioma BTPCs can be hindered by the depletion of HIF-1α or inactivation of Notch signaling, partly because of the interaction between HIF-1α and NICD." (PMID 25601901, 2014). "Loss-of-function causes decreased α-KG and NADH, and the decreased α-KG results in an increased hypoxia inducible factor 1 alpha (HIF-1α) which promotes glioma development." (PMID 24728830, 2014). "In vitro, the expressions of HIF-1α, Notch1, Flk1, and p-Flk1 in transdifferentiation-induced C6 glioma cells were significantly higher than the control." (PMID 24722469, 2014). "As HIF-1α is well known as a key regulator of VEGF expression, we examined the effects of ATRA on HIF-1α expression in glioma cells." (PMID 23554794, 2013). "Hypoxia-induced HIF-1α reduces migration potential and sphere formation in glioma cells and expansion of CD133+ CSCs in glioblastoma." (PMID 23314174, 2013).
glioma (continued). "As such, lactate and pyruvate have been shown to regulate hypoxia-inducible gene expression independently of hypoxia by stimulating the accumulation of HIF1A in human gliomas and other cancer cell lines." (PMID 24086109, 2013). "Since VEGF is well known to be regulated by HIF-1α, the effect of ATRA on HIF-1α mRNA transcription in glioma cells was examined by real-time PCR." (PMID 23554794, 2013). "In some studies, artemisinin decreased HIF1α expression in mouse embryonic stem cell-derived embryoid bodies, Rheumatoid arthritis fibroblast-like synoviocytes, and C6 glioma cells." (PMID 22900042, 2012). "Knockdown of HIF-1α abrogated the hypoxia-mediated CD133-positive cancer stem cell expansion in gliomas." (PMID 22363512, 2012). "ER-400583-00 suppressed the production of HIF-1α protein in response to hypoxia, with a half-maximal inhibitory concentration value of 3.7 nM in human U251 glioma cells." (PMID 22211243, 2012). "Rt-glioma cells and Rt-NSCs each expressed Hif-1α (mRNA and protein) and up-regulated the Hif gene target, Vegf, confirming that a hypoxic response had successfully been induced." (PMID 22905089, 2012). "The disruption of HIF-1α by the intratumoral injection of small-interfering RNA (siRNA) was reported to result in the regression of human glioma xenografts, and in the tumor stasis of human cervical cancer and colon cancer xenografts." (PMID 22211243, 2012). "The downregulation of HIF-1α consistently increased the sensitivity of human glioma cells to doxorubicin and etoposide." (PMID 21906280, 2011). "Recently, our group showed that the silencing of HIF-1α by siRNA or chetomin resulted in a significantly enhanced cytotoxicity and radiosensitivity in both human glioma cell lines, in addition to HT1080 human fibrosarcoma cells." (PMID 21906280, 2011). "In this study, we analyzed the effects of BA on the cytotoxicity, migration, protein expression of PARP, survivin and HIF-1α and radiosensitivity under normoxic and hypoxic conditions in the radioresistant glioma U251MG and U343MG cell lines." (PMID 21906280, 2011). "In human glioma cells, the activation of HIF-1α enhances CD133+ glioma-derived cancer stem cell expansion by increasing self-renewal activity and inhibiting cell differentiation." (PMID 22145042, 2011). "In our experiments, the accumulation of HIF-1α observed after treatment with 3NPA also indicates an intact citric acid cycle in the glioma cell lines." (PMID 21791085, 2011). "This study shows that knock down of HIF-1α in glioma cells results in i) reduced migration in vitro, ii) decreased invasion in vivo, iii) reduced ability to form tumor spheres and iv) altered gene expression profiles under hypoxic conditions." (PMID 20515450, 2010). "To study the role of HIF-1α and hypoxia in glioma cell migration we analyzed the ability of stable transfectants expressing shHIF to migrate under both normoxic and hypoxic conditions using the Boyden chamber assay." (PMID 20515450, 2010). "This is the first study showing that inhibition of HIF-1α by siRNA or by CTM under hypoxic conditions resulted in a significantly enhanced radiosensitivity of the human glioma cells." (PMID 21050481, 2010). "To further elucidate the role that HIF-1α has in glioma cell migration in vitro and in vivo, we knocked down the expression of HIF-1α and evaluated the migration and invasion potential of these glioma cells." (PMID 20515450, 2010). "In order to understand the role that HIF-1α plays in glioma cell invasion, we used a shRNA approach to knock down its expression." (PMID 20515450, 2010). "To accomplish this, we used stable transfectants (shHIF and control) of both human (LN308 and U87MG) and murine (GL261) glioma cell lines and compared the levels of expression of HIF-1α under both normoxic and hypoxic conditions." (PMID 20515450, 2010). "Our data show that inhibition of HIF-1α by expression of a stable shRNA alters the growth pattern of glioma cells in the brain microenvironment." (PMID 20515450, 2010).
glioma (continued). "In all cases, the control glioma cells showed significantly higher numbers of migrated cells under normoxic conditions compared with cells knocked down for HIF-1α expression (p < 0.0001)." (PMID 20515450, 2010). "In contrast, when HIF-1α expression was knocked down in human and murine glioma cells the levels of HIF-1α were lower in normoxic conditions and failed to become upregulated in hypoxic conditions." (PMID 20515450, 2010). "Some studies showed that reduction of HIF-1α levels by siRNA in glioma cells grown in mouse flanks decreased tumor growth which was associated with reduction of VEGF and GLUT-1, two known downstream targets of HIF-1α." (PMID 20515450, 2010). "Our previous studies using the glioma cell line U87MG supported the potential usefulness of HIF-1α as an endogenous marker of tumor hypoxia and of resulting radioresistance of human tumor cells." (PMID 21050481, 2010). "Our data show that knock down of HIF-1α in glioma cells significantly impairs their migration in vitro as well as their ability to invade into the brain parenchyma in vivo." (PMID 20515450, 2010). "Glioma cells with reduced HIF-1α expression and their response to hypoxia results in cells with reduced migration ability, overall less invasive tumors, and reduced ability to form tumor spheres." (PMID 20515450, 2010). "Further, silencing of HIF-1α by siRNA sensitized glioma cells to the chemotherapeutic agents doxorubicin and etoposide." (PMID 21050481, 2010). "Immunohistochemical expression of HIF-1α clearly correlated with the degree of glioma malignancies and predicted survival among patients with malignant gliomas and the degree of necrosis on MRI (data not shown)." (PMID 20414463, 2010). "Our data show that knock down of HIF-1α in human and murine glioma cells impairs their migration in vitro and their invasion in vivo." (PMID 20515450, 2010). "Our data show that knock down of HIF-1α in human and murine glioma cells impairs their migration in vitro and their invasion into the brain parenchyma in vivo." (PMID 20515450, 2010). "Downregulation of HIF-1α in glioma cells using siRNA resulted in growth inhibition and an angiosuppressive effect on glioma growth (unpublished data)." (PMID 20414463, 2010). "The shRNA approach directed towards HIF-1α resulted in reduced migration of human and murine glioma cells knocked down for HIF-1α compared with control cells with normal HIF-1α expression." (PMID 20515450, 2010). "The HIF-1α/FLuc and HIF-1α(ΔODDD)/Fluc fusion proteins expression in NIH3T3 fibroblasts was compared to that obtained in reporter-transduced U87 glioma cells." (PMID 19347037, 2009). "The importance of these pathways is also evidenced by the utility of VEGF and HIF1A inhibitors in decreasing glioma growth and prolonging survival in vivo." (PMID 19732454, 2009). "This has been suggested by experimental findings of needle electrode measurements of human glioma and by immunohistochemical studies using HIF-1α or carbonic anhydrase IX (CA IX) as an endogenous hypoxia marker or EF5 as an injectable hypoxia marker." (PMID 17597534, 2007). "HIF-1α expression varies among glioblastoma grade, while HIF-1α expression is mainly located in the cytosol in low-grade gliomas (slow growing), contrasting to high-grade (faster growing), where HIF-1α is distinctively strong in the neighboring areas of necrosis, mostly found in nuclei." (PMID 40277699, 2025). "This suggests that HIF-1α may contribute to glioma's malignant progression by upregulating CD47 expression." (PMID 39781344, 2025). "Moreover, the inhibition of HIF-1α sensitizes glioma cells to temozolomide, as reported in HIF-1α knocked-down cell models." (PMID 40277699, 2025). "Additionally, we utilized GEPIA to visualize HIF-1α expression levels in both low-grade glioma and high-grade glioma, establishing that HIF-1α exhibited overexpression in glioma relative to normal controls." (PMID 39781344, 2025).
glioma (continued). "Moreover, elevated expression of HIF-1α has been correlated with poor prognosis and higher tumor grade in gliomas." (PMID 41155273, 2025). "Furthermore, overexpression of PAX6 can increase the concentration of Fe2+ within glioma cells, while overexpression of HIF-1α has the opposite effect." (PMID 41154694, 2025). "Preclinical studies suggest that propofol may inhibit glioma cell proliferation, invasion, and migration and promote apoptosis through mechanisms such as the upregulation of microRNA-218 and suppression of HIF-1α and MMP-2 activity." (PMID 40870507, 2025). "Analysis of the HIF1A gene promoter region revealed the presence of the MXD1 recognition motif 5’-CACGTG-3’, suggesting MXD1 may negatively regulate HIF-1α expression and modulate VM formation in gliomas." (PMID 40140670, 2025). "We next examined HIF-1α expression in human glioma tissue arrays." (PMID 41154694, 2025). "Notably, HIF-1α has been presumed to drive glioma progression from low-grade to GBM, as mRNA and protein expression have been linked to a higher pathological tumor grade and poor prognosis." (PMID 40277699, 2025). "Consequently, it is imperative to investigate the influence of the regulatory interaction between PAX6 and HIF-1α in glioma formation and development." (PMID 41154694, 2025). "In this respect, we believe that GAL-8, ITGβ-1, and HIF-1α may be usable as a panel of non-invasive biomarkers for glioma diagnosis." (PMID 40512281, 2025). "Additionally, the mechanisms of the LOX family in gliomas, including interactions with HIF-1α and TGF-β signaling pathways, require further exploration." (PMID 40270974, 2025). "Furthermore, we explored the potential mechanistic role of PAX6 dysregulation in modulating HIF-1α and ferroptosis in gliomas." (PMID 41154694, 2025). "Interestingly, it has also been shown that targeting mitochondrial function and OXPHOS can destabilize hypoxia-inducible factor 1-alpha (HIF-1α), a critical regulator of glioma progression under hypoxic conditions." (PMID 41008904, 2025). "The results of the present study revealed that VH032 plays a crucial role in antitumour effects on glioma cells in vitro by inhibiting the VHL/HIF-1α/VEGF signalling pathway and interfering with the proliferation, invasion, migration, apoptosis and cycle distribution of glioma cells." (PMID 41030787, 2025). "Moreover, borneol has been identified as a sensitizer of glioma cells to radiation, achieved through the induction of autophagy mediated by inhibition of the mTORC1/eIF4E/HIF‐1α regulatory axis." (PMID 39803277, 2025). "Immunohistochemistry demonstrated that HIF-1α expression increased with glioma grade." (PMID 41154694, 2025). "The relationship between PD-L1 and HIF1α in glioma could explain the influence of hypoxia on tumor immune escape." (PMID 38786726, 2024). "Whether HIF-1α promotes the malignant evolution of glioma through the pyroptosis program remains to be further investigated." (PMID 38734702, 2024). "HIF-1α expression is significantly elevated in gliomas and positively correlates with malignancy." (PMID 38734702, 2024). "This suggests that overexpression of the HIF-1α gene may promote the increase in the malignant degree of glioma." (PMID 38734702, 2024). "The expression of HIF-1α in high-grade gliomas was stronger than that in low-grade gliomas." (PMID 38734702, 2024). "More importantly, we confirmed the existence of a HIF-1α/LAMC1 axis in the glioma hypoxic microenvironment, which may be a major mechanism regulating its malignant phenotype." (PMID 38678297, 2024). "Notably, within the subset of IDH wt gliomas in the CGGA and TCGA databases, higher levels of HIF1α and CA9 expression were linked to worse patient survival." (PMID 39346536, 2024). "Therefore, the increase in LAMC1 expression in glioma was at least partly mediated directly through HIF-1α." (PMID 38678297, 2024).
glioma (continued). "Notably, siRNA against HIF-1α can reduce the ability of murine glioma cells to migrate accompanied by decreased immunophenotype levels of HIF-1α transcriptional targets, including among others VEGF, and CA-IX." (PMID 39055895, 2024). "Hypoxia downregulated the expression of IDE, another peptidase known to degrade Aβ, in U87 glioma cells, but the potential roles of HIF-1α remain unclear." (PMID 39594520, 2024). "However, few reports exist pertaining to the effect of borneol on, and the role of HIF-1α in the chemosensitivity of gliomas." (PMID 38188151, 2024). "HIF-1α is a transcription factor that activates multiple glioma survival signaling pathways." (PMID 39201395, 2024). "In accordance with previous studies, borneol inhibited HIF-1α expression by regulating the mTORC1/eIF4E pathway, and we found that borneol might make glioma cells sensitive to TMZ by promoting HIF-1α autophagic degradation." (PMID 38188151, 2024). "Importantly, HIF-1α levels correlated with prognosis, as glioma patients expressing higher levels of HIF-1α showed a median survival 10 months shorter than patients expressing lower levels of HIF-1α (15.6 vs 25.6 months, respectively)." (PMID 38341408, 2024). "Previous studies have also proven that borneol can improve radiotherapy efficacy in glioma, and its mechanism might be related to the downregulation of hypoxia inducible factor-1 (HIF-1α) expression." (PMID 38188151, 2024). "Most TCGA solid cancers including glioma showed enhancement of HIF-1α expression." (PMID 38678297, 2024). "Combined with the relationship between miR-18a, hypoxia and glioma, miR-18a may influence the occurrence and development of glioma by inhibiting the expression of HIF1A." (PMID 38879468, 2024). "HIF-1α might be a valid therapeutic target of borneol, which can be potentially applied as a chemosensitizing drug used for glioma treatment." (PMID 38188151, 2024). "Here, our study showed that borneol can improve TMZ chemotherapy sensitivity, and that HIF-1α is a potential target for improving the antitumor efficacy of TMZ, which is closely related to the promotion of the autophagic degradation of HIF-1α, thus improving chemotherapy sensitivity in glioma cells." (PMID 38188151, 2024). "Besides, HIF-1α correlates with a higher tumour grade and have been pinpointed as a driver from low-grade gliomas to GBM." (PMID 38341408, 2024). "We analyzed the importance of HIF1A in glioma via TCGA and our tissue microarray." (PMID 37988165, 2023). "HIF-1α has been shown to play a key role in the development and progression of gliomas." (PMID 38067243, 2023). "Moreover, enhancement of stem-ness property in glioma and leukemia CSCs because of HIF-1α activation has been reported." (PMID 37328876, 2023). "Moreover, the HIF-1α inhibitor PX-478, combined with anti–PD-L1 treatment, can reverse the immunosuppressive microenvironment in gliomas." (PMID 37906252, 2023). "We further demonstrated that NCX2 impaired cell invasion through the HIF-1α pathway in glioma." (PMID 36334237, 2023). "It is suggested that NUDT1 may play an important role in tumorigenesis of glioma by activating the expression of HIF-1α." (PMID 37086071, 2023). "This suggests that in the hypoxic environment of glioma, oncolytic viruses might enhance the immunosuppressive functions of Tregs by eliminating HIF-1α, even though hypoxia could also promote the replication of the virus." (PMID 37234776, 2023). "In another study investigating the expression of VEGFR2 after treatment with hesperidin in a mouse model of glioma, it was shown that hesperidin (20 mg/kg) could significantly inhibit the HIF‐1a/VEGF/VEGFR2 pathway." (PMID 37581480, 2023).